AMY1C (amylase alpha 1C)
Description:
Calcium-binding enzyme that initiates starch digestion in the oral cavity. Catalyzes the hydrolysis of internal (1->4)-alpha-D-glucosidic bonds, yielding a mixture of maltose, isomaltose, small amounts of glucose as well as small linear and branched oligosaccharides called dextrins.
Synonyms: AMY1
Tractability: Small molecule: it belongs to a druggable protein family. Antibody: UniProt places it where antibodies can reach, with high confidence; UniProt predicts a signal peptide or a membrane-spanning region; its Gene Ontology location is reachable by antibodies, with medium confidence.
Gene: Protein-coding gene on chromosome 1 (103,745,126 to 103,758,726, forward strand). Ensembl gene ENSG00000187733.
Subcellular location: Secreted
Subcellular location (Human Protein Atlas): Cytosol; Golgi apparatus; Predicted to be secreted
Pathways (Reactome):
Digestion and absorption: Digestion of dietary carbohydrate
Gene Ontology:
Molecular function: alpha-amylase activity; calcium ion binding; chloride ion binding; catalytic activity; cation binding
Biological process: oligosaccharide metabolic process; carbohydrate metabolic process
Cellular component: extracellular exosome; extracellular region
Genetic constraint (gnomAD): Loss-of-function variants: 0 observed, 5.31 expected, observed/expected ratio (o/e) 0, 90% interval 0 to 0.56. That is too few expected variants to judge how well the gene tolerates losing a copy. Missense variants: 2 observed, 32.99 expected, observed/expected ratio (o/e) 0.0606, 90% interval 0.024 to 0.19. Synonymous variants: 1 observed, 10.25 expected, observed/expected ratio (o/e) 0.0976, 90% interval 0.034 to 0.46.
Homologues: Orthologues: macaque AMY2B (94% identical), tropical clawed frog amy2a (77% identical), tropical clawed frog amy2b (75% identical), Drosophila melanogaster Amy-p (53% identical), Drosophila melanogaster Amy-d (52% identical), Caenorhabditis elegans C50B6.7 (47% identical), Drosophila melanogaster Amyrel (47% identical), Drosophila melanogaster Mal-A7 (16% identical), Drosophila melanogaster Mal-A4 (15% identical), Drosophila melanogaster Mal-B2 (14% identical), Drosophila melanogaster Mal-A2 (14% identical), Drosophila melanogaster Mal-A8 (14% identical), and 3 more. Paralogues in human: AMY1A (100% identical), AMY1B (100% identical), AMY2B (97% identical), AMY2A (97% identical), SLC3A1 (17% identical), GBE1 (15% identical), SLC3A2 (13% identical).